DHODH (dihydroorotate dehydrogenase (quinone))
Diseases named in the same sentence as DHODH in open-access papers (continued):
Sharing a sentence is not in itself a finding about the gene and the disease.
DHODH also shares sentences with these, for which no sentence is quoted: triple-negative breast carcinoma (3 papers); atherosclerosis (2); brain tumor (2); lipid metabolic disorders (2); prostate carcinoma (2); renal cell carcinoma (2); type 2 diabetes (2); viral diseases (2); actinic keratosis (1); acute kidney injury (1); alopecia areata (1); aneuploidy (1); ankylosis (1); cholangiocarcinoma (1); chronic lymphocytic leukemia (1); cognitive deficits (1); colitis (1); cystoid macular edema (1); eyelid coloboma (1); Hyperkeratosis (1); inflammatory bowel disease (1); metastatic tumors (1); myelodysplastic syndrome (1); myocardial hypertrophy (1); non-melanoma skin carcinoma (1); oral cancer (1); oral squamous cell carcinoma (1); orotic aciduria (1); palate cleft lip (1); Pan (1).
A further 16 diseases each share a sentence with DHODH in 1 paper.